TM2D3 (TM2 domain containing 3)
Description:
Positive regulator of Notch signaling, required for activation of NOTCH1 intracellular processing and NOTCH1 localization to the cell membrane.
Synonyms: BLP2; FLJ22604; NCRMS
Tractability: Antibody: UniProt predicts a signal peptide or a membrane-spanning region; its Gene Ontology location is reachable by antibodies, with medium confidence. PROTAC: ubiquitination databases record sites on it.
Gene: Protein-coding gene on chromosome 15 (101,621,444 to 101,652,391, reverse strand). Ensembl gene ENSG00000184277.
Subcellular location: Cell membrane; Cytoplasmic vesicle; Endoplasmic reticulum; Membrane
Subcellular location (Human Protein Atlas): Nucleoplasm; Cytosol
Gene Ontology:
Molecular function: protein binding
Biological process: lateral inhibition; Notch receptor processing, ligand-independent; positive regulation of Notch signaling pathway; positive regulation of protein localization to cell surface
Cellular component: cytoplasmic vesicle; plasma membrane; endoplasmic reticulum; membrane
Genetic constraint (gnomAD): Loss-of-function variants: 33 observed, 28.08 expected, observed/expected ratio (o/e) 1.17, 90% interval 0.89 to 1.57. The upper end of that interval is the gene's LOEUF score, 1.57, which puts it in group 6 of 6, group 1 being the genes least tolerant of losing a copy. Missense variants: 364 observed, 331.97 expected, observed/expected ratio (o/e) 1.1, 90% interval 1.01 to 1.2. Synonymous variants: 138 observed, 126.73 expected, observed/expected ratio (o/e) 1.09, 90% interval 0.95 to 1.25.
Homologues: Orthologues: chimpanzee TM2D3 (99% identical), pig TM2D3 (92% identical), guinea pig TM2D3 (88% identical), mouse Tm2d3 (87% identical), rat Tm2d3 (87% identical), rabbit TM2D3 (83% identical), macaque TM2D3 (83% identical), tropical clawed frog tm2d3 (68% identical), dog TM2D3 (62% identical), zebrafish tm2d3 (54% identical), Drosophila melanogaster amx (43% identical), Caenorhabditis elegans C41D11.9 (35% identical). Paralogues in human: TM2D1 (25% identical), TM2D2 (23% identical).
Diseases named in the same sentence as TM2D3 in open-access papers:
TM2D3 is named in the same sentence as 1 disease in open-access papers, as found by Europe PMC text mining. Sharing a sentence is not in itself a finding about the gene and the disease. The quoted sentences say what the papers report.
Alzheimer disease (2 papers, 2021 to 2022). A progressive, neurodegenerative disease characterized by loss of function and death of nerve cells in several areas of the brain leading to loss of cognitive function such as memory and language. "A rare missense variant (P155L) in TM2D3 is significantly associated with an increased risk of developing late-onset Alzheimer’s disease and an earlier age of onset." (PMID 36346359, 2022). "Rare variants in TM2D3 are associated with Alzheimer’s disease (AD) and its fly ortholog almondex is required for embryonic Notch signaling." (PMID 34905536, 2021). "Considering that TM2D3 affects Notch signaling and Alzheimer’s disease, the γ-secretase that plays crucial roles in both events may be a target of TM2D3." (PMID 36346359, 2022).